SFN (stratifin)
Diseases named in the same sentence as SFN in open-access papers (continued):
Sharing a sentence is not in itself a finding about the gene and the disease.
lung adenocarcinoma (continued). "However, according to the multistep carcinogenesis of lung adenocarcinoma, the number of such driver oncogenes in early-stage lung adenocarcinoma is expected to be limited, and SFN overexpression is one of the candidates suggested playing an important role in forced cell proliferation." (PMID 26223682, 2015). "The ToppFun FEA, relative to diseases, predicted a possible association of the RAC1, CFH and 5 of the 14-3-3 protein family genes, namely SFN, YWHAB, YWHAE, YWHAG and YWHAZ with lung adenocarcinoma." (PMID 35366267, 2021). "Next, to investigate the expression pattern and clinicopathological implications of SFN, GORASP2 and ZYG11A, we performed IHC using 171 cases of lung adenocarcinoma." (PMID 30899432, 2019). "Furthermore, they found that SFN enhances receptor tyrosine kinases stabilization by aberrant ubiquitin-specific protease 8 (USPB) regulation in lung adenocarcinoma, implying that SFN could be an appropriate therapeutic target for lung adenocarcinoma than USP8." (PMID 30926680, 2019). "Recently we have reported that SFN stabilizes receptor tyrosine kinases such as EGFR and MET by facilitating their deubiquitination in lung adenocarcinoma cells." (PMID 30899432, 2019). "Although the oncogenic activity of SFN is weaker than that of EML4-ALK fusion kinase, SFN also appears to have the potential to initiate lung adenocarcinoma." (PMID 26223682, 2015). "The analysis of the effects from each gene expression on survival outcome indicated that 6 genes (AGR2, SPDEF, CDKN2A, CLDN3, SFN, and PHLDA2) play oncogenic roles, and 7 genes (PDK4, FMO2, CPED1, GNG11, IL33, BTNL9, and FABP4) act as tumor suppressors in lung adenocarcinoma." (PMID 29285217, 2017). "Since alteration of SFN is observed in most lung adenocarcinomas, even AIS and minimally invasive adenocarcinoma, targeted therapy to block SFN might be a new treatment strategy for patients with early-stage lung adenocarcinoma." (PMID 26223682, 2015). "This is likely because SFN does not bind to proteins such as BAX or BAD, which regulate apoptosis or senescence in lung adenocarcinoma (data not shown, personal communication)." (PMID 26223682, 2015).
ovarian carcinoma (8 papers, 2012 to 2023). A malignant neoplasm originating from the surface ovarian epithelium. "Overexpression of SFN has been reported in many human tumors, such as ovarian cancer, breast cancer, lung cancer, and HCC." (PMID 37587914, 2023). "SFN is also a prognostic factor for many malignant tumors, such as ovarian cancer, glioma, and gallbladder cancer." (PMID 37587914, 2023). "We detected the relationship between SFN expression and OS of ovarian cancer patients received different chemotherapy drug." (PMID 30926680, 2019). "Considering that chemotherapy and cytoreductive surgery remained the gold standards of ovarian cancer treatment, we focussed on the relationship between SFN expression and OS of ovarian cancer patients received different chemotherapy drug." (PMID 30926680, 2019). "We exhibited the expression levels of SFN in different kinds of ovarian cancer with those in control samples by exploring the Oncomine database." (PMID 30926680, 2019). "The comparisons of mRNA levels of SFN in ovarian cancer and healthy samples in each individual dataset were performed by using the Student’s t test." (PMID 30926680, 2019). "Although SFN expression was not significantly correlated with poor overall survival, the higher expression of SFN in all patients with ovarian cancers is remarkably correlated with the better PFS and worse PPS." (PMID 30926680, 2019). "The higher expression of SFN in all patients with ovarian cancers is significantly correlated with worse postprogression survival." (PMID 30926680, 2019). "In the current analysis, we investigated the expression and prognosis of SFN and its coexpression gene in ovarian cancer for the first time by using bioinformatics." (PMID 30926680, 2019). "Our studies detected the expression of SFN in ovarian cancer by Oncomine, Human Protein Atlas database and ULCAN database." (PMID 30926680, 2019). "It has been reported that the expression of SFN is frequently lost in various types of human diseases including ovarian cancer, uterine papillary serous carcinoma, uterine leiomyomas, ovarian granulosa cell tumors and steroid cell tumors." (PMID 26181055, 2015). "And MICB was co-up-regulated with SFN in ovarian cancer, which was confirmed by the GEPIA database, suggesting that SFN could be associated with the MICB in ovarian cancer." (PMID 30926680, 2019). "Based on above results, overexpression of SFN was correlated with the prognosis in ovarian cancer." (PMID 30926680, 2019). "The present study might be useful for better understanding the clinical significance of SFN mRNA and provided a potential therapeutic target for ovarian cancer research in the future." (PMID 30926680, 2019). "Moreover, we investigated the correlation between the expression levels of SFN and the clinicopathological parameters of ovarian cancer patients based on different subtypes." (PMID 30926680, 2019). "As for ovarian cancer, current research just indicated that SFN was one of highly overexpressed genes in ovarian cancer and normal ovarian epithelium and may involve in regulation network of ovarian cancer." (PMID 30926680, 2019). "Although SFN expression was not significantly correlated with poor overall survival, the higher expression of SFN in all patients with ovarian cancers is significantly correlated with the better progression-free survival (PFS) and worse postprogression survival (PPS) (P<0.05)." (PMID 30926680, 2019). "In the view of the huge number of ovarian cancer patients, SFN could be a potential prognostic marker for ovarian patients who received chemotherapeutics." (PMID 30926680, 2019). "First, we investigated the expressions and prognosis value of SFN and MICB in ovarian cancer from several public databases." (PMID 30926680, 2019). "These genes include stratifin (SFN), immunoglobulin binding protein 1 (IGBP1), ovarian carcinoma immunoreactive antigen domain 2 (OCIAD2), and dimethylarginine dimethylaminohydrolase 2 (DDAH2)." (PMID 30899432, 2019).
ovarian carcinoma (continued). "In human ovarian carcinoma SKOV3 and A2780 cells, the expression of SFN and its coexpression gene MICB were also increased at protein and mRNA levels compared with the normal ovarian epithelial cells." (PMID 30926680, 2019). "In summary, SFN and its coexpressed gene MICB were significantly increased in multiple types of ovarian cancer." (PMID 30926680, 2019). "Second, the upstream molecule on the roles of SFN in ovarian cancer lack of further exploration." (PMID 30926680, 2019).
breast tumor (7 papers, 2005 to 2022). "SFN (stratifin 14-3-3) was first described as a tumor suppressor gene silenced in most breast tumors, but it has also been described as determinant for breast tumor invasion and associated with poor clinical outcome." (PMID 35625825, 2022). "SFN is located on 1p36.11 and is encoded by a single 747 base pair (bp) exon; 1p36 is a target of loss of heterozygosity in 16% to 37% of sporadic breast tumours and in 32% to 35% of familial tumours." (PMID 16280053, 2005). "The same study also reported that LAD1 physically interacted with stratifin (14–3-3σ), which promoted breast tumor invasion by regulating actin filament turnover." (PMID 33267790, 2020). "SFN is a negative regulator of cell cycle progression and is suggested to have an important function in preventing breast tumour cell growth, particularly at the G2 cell cycle checkpoint." (PMID 16280053, 2005). "The expression of ABHD11, ADORA2B, E2F1, EZH2, PAICS, SFN and SH3GL1 was significantly higher in grade III than in grade I breast tumors." (PMID 28411283, 2017). "Interestingly, there is a nine-fold decreased expression of SFN in BRCA1- and BRCA2-related tumours compared to sporadic breast tumours." (PMID 16280053, 2005).
cervical cancer (7 papers, 2016 to 2024). A primary or metastatic malignant neoplasm involving the cervix. "This pivotal conclusion not only provides a theoretical foundation but also furnishes empirical evidence to support subsequent investigations targeting SFN as a means to decipher the underlying mechanisms and devise therapeutic interventions against cervical cancer cell metastasis." (PMID 37946061, 2024). "Unfortunately, this study only elaborated the mechanism of SFN regulating cervical cancer cell metastasis at the cellular level." (PMID 37946061, 2024). "We established SFN overexpression and SFN silencing cellular models to assess the invasive and migratory capabilities of cervical cancer cells using transwell and scratch assays." (PMID 37946061, 2024). "SFN can regulate cervical cancer cell proliferation, apoptosis, cytoskeletal remodeling and metastasis through LIMK2/Cofilin signaling." (PMID 37946061, 2024). "In cervical cancer research, the expression of SFN in squamous cell carcinoma is significantly higher compared to adenocarcinoma." (PMID 37946061, 2024). "Western blot experiments demonstrated the successful establishment of SFN-overexpressing (SFN-OE) and SFN-silencing (SFN-siRNA) cellular models for manipulating SFN expression in cervical cancer cells." (PMID 37946061, 2024). "In this study, the expression of SFN in cervical cancer tissues was significantly higher than that in normal tissues." (PMID 37946061, 2024). "SFN overexpression was observed to enhance invasion and migration of cervical cancer cells, induce cytoskeletal remodeling, facilitate cell proliferation, and suppress apoptosis." (PMID 37946061, 2024). "Up-regulation of SFN expression promoted the proliferation, cytoskeletal remodeling, migration and invasion of cervical cancer cells, and enhanced the expression of p-LIMK2, LIMK2, Cofilin and p-Cofilin." (PMID 37946061, 2024). "Immunohistochemical analysis revealed an upregulation of SFN expression in cervical cancer tissues compared to normal cervical tissues." (PMID 37946061, 2024). "SFN can regulate cervical cancer cell proliferation, cytoskeletal remodeling and metastasis through LIMK2/Cofilin signaling." (PMID 37946061, 2024). "These compelling results provide compelling evidence to support the notion that SFN exerts a regulatory influence on the proliferative capacity of cervical cancer cells." (PMID 37946061, 2024). "Through our experimental investigations, it becomes evident that SFN exhibits regulatory control over crucial aspects of cervical cancer cell behavior, encompassing proliferation and apoptosis, invasion, and metastasis." (PMID 37946061, 2024). "In the future, we will further confirm the mechanism of SFN in cervical cancer progression and tumor immunity using animal models." (PMID 37946061, 2024). "Results from Transwell and scratch assays demonstrated that SFN-OE enhanced the invasive and migratory capacities of Caski and SiHa cells, whereas SFN knockdown inhibited the invasion and migration of cervical cancer cells." (PMID 37946061, 2024). "In this study, we compared the expression of SFN in normal cervical tissues and cervical carcinoma tissues." (PMID 37946061, 2024). "Our results complement the current mechanism of action by which SFN regulates the development and progression of cervical cancer cells through the LIMK2/Cofilin signaling pathway, providing a potential target for cervical cancer treatment." (PMID 37946061, 2024). "LINC01128, a novel lncRNA, has been shown to promote cell proliferation, migration, and invasion, inhibit cell apoptosis, sponge miR-383-5p, thus upregulating the expression of SFN in cervical cancer." (PMID 35193567, 2022). "For instance, LINC01128 facilitates cervical cancer by functioning as a sponge of miR-383-5p, thus enhancing the SFN expression and promoting cell proliferation, migration, and invasion." (PMID 35571024, 2022).
cervical cancer (continued). "Hu Y and his colleagues reported that LINC01128 expedites cervical cancer progression by regulating miR‐383‐5p/SFN axis." (PMID 33108067, 2020). "SFN plays an important role in the diagnosis of cervical cancer." (PMID 37946061, 2024). "Interestingly, SFN can affect cytoskeletal remodeling of cervical cancer, and this effect is closely related to metastasis." (PMID 37946061, 2024). "Knockdown of SFN diminished cervical cancer cell metastasis and conversely; hence SFN is more likely a positive regulator of metastasis; it could be considered as a potential biomarker of the progression of cervical cancer." (PMID 37946061, 2024). "This study aims to investigate whether SFN regulates the metastasis of cervical cancer cells through the LIMK2/Cofilin signaling pathway." (PMID 37946061, 2024). "Importantly, elucidating the mechanism of action of SFN in cervical cancer cell metastasis is the focus of this study." (PMID 37946061, 2024). "Therefore, we speculate that SFN is high likely to regulate the development and progression of cervical cancer cells through LIMK-Cofilin signaling pathway." (PMID 37946061, 2024). "SFN knockdown significantly reduced the migration and invasion of cervical cancer cells, down-regulated the expression of p-LIMK2, LIMK2, Cofilin and p-Cofilin, inhibited cytoskeletal remodeling, and increased the apoptosis index of cervical cancer cells." (PMID 37946061, 2024). "Based on these observations, it is reasonable to think that SFN may regulate cervical cytoskeletal remodeling through LIMK2/Cofilin pathway and affect the metastasis of cervical cancer cells." (PMID 37946061, 2024). "Notably, the SFN and LIMK2/Cofilin signaling pathways converge to actively participate in the remodeling of the cellular cytoskeleton, thus suggesting a plausible mechanism by which SFN orchestrates cervical cancer cell metastasis via modulation of the LIMK2/Cofilin signaling pathway." (PMID 37946061, 2024).
glioma (6 papers, 2017 to 2025). A benign or malignant brain and spinal cord tumor that arises from glial cells (astrocytes, oligodendrocytes, ependymal cells). "And CCNA1, DTL, and SFN were discovered as novel biomarkers for glioma diagnosis, treatment, and prognosis evaluation." (PMID 36092717, 2022). "Stratifin (SFN, 14-3-3 sigma), as an oncogene related to cell proliferation, facilitates the development and progression of a variety of cancers including gliomas and has the potential to be a new therapeutic target." (PMID 33042807, 2020). "However, the downregulation of SFN has also been observed in gliomas, the nervous system, and the reproductive system." (PMID 37587914, 2023). "In summary, CCNA1, DTL, and SFN could serve as a new biomarker for glioma diagnosis, treatment, and prognosis evaluation." (PMID 36092717, 2022).
pancreatic cancer (6 papers, 2014 to 2025). "In ROC analysis, SFN expression showed excellent (AUC = 0.917) diagnostic value of pancreatic cancer." (PMID 35547358, 2022). "SFN (Stratifin) is over-expressed and hypomethylated in cancer tissues compared with normal ducts and plays a role as an oncogene in pancreatic cancer." (PMID 40362181, 2025). "The results showed that SFN was upregulated in seven cancer types, namely, bladder, head and neck, kidney, liver, lung, ovarian, and pancreatic cancers." (PMID 35547358, 2022). "Third, this study cannot explain how the tissue-specific upregulation SFN gene is related to pancreatic cancer." (PMID 35547358, 2022). "ATM serine/threonine kinase (ATM), stratifin (SFN), and growth arrest and DNA damage 45 alpha (GADD45A), which would be activated and arrest cell cycle in response to DNA damage, were up-regulated in pancreatic cancer cells after anlotinib treatment." (PMID 33748143, 2021). "Moreover, biocomputational tools allowed to demonstrate that among the most differentially expressed genes in pancreatic cancer were Mesothelin, Muc4, Muc5A/C, Kallikrein 10, Transglutaminase 2, Fascin, TMPRSS3 and Stratifin." (PMID 25275504, 2014).
colorectal cancer (5 papers, 2018 to 2024). A primary or metastatic malignant neoplasm that affects the colon or rectum. "Some studies, however, have found SFN expression to be increased in some head and neck cancers and have demonstrated SFN as an independent prognostic marker for poor survival in colorectal cancer patients." (PMID 30404157, 2018). "Therefore, tezacaftor probably repressed the expression of the SFN gene and led to colorectal cancer progression, which supported our results in HT-29." (PMID 38528462, 2024). "However, many conflicting studies have represented upregulation of SFN in the head and neck, gastric, pancreas, and colorectal cancers." (PMID 36160032, 2022). "Controversial studies reported the role of SFN in potentiating colon tumorigenesis through the activation of various factors, such as matrix metalloproteinase 28 (MMP28), which contributed to the progression of colorectal cancer." (PMID 38528462, 2024). "Our quantitative PCR results demonstrated that tezacaftor might promote SFN gene expression in HCT-116 cells, preventing colorectal cancer progression." (PMID 38528462, 2024).
hepatocellular carcinoma (5 papers, 2015 to 2023). A malignant tumor that arises from hepatocytes. "Abnormal stratifin (SFN) expression is closely related to the progression of several human cancers, but the potential roles of SFN in hepatocellular carcinoma (HCC) remain largely unknown." (PMID 37587914, 2023). "These subgroups also exhibited differential expression of SFN and PDK4, which may contribute to a better understanding of the biology underlying hepatocellular carcinoma." (PMID 37398672, 2023). "Several studies have indicated that 14-3-3β, 14-3-3ε, 14-3-3γ, 14-3-3σ (also known as stratifin) and 14-3-3ζ isoforms are overexpressed in hepatocellular carcinoma (HCC)." (PMID 26083935, 2015).
esophageal squamous cell carcinoma (4 papers, 2015 to 2022). Esophageal squamous cell carcinoma (ESCC) is a type of esophageal carcinoma (EC) that can affect any part of the esophagus, but is usually located in the upper or middle third. "Downregulation of SFN has been associated with multistage carcinogenesis and poor prognosis in salivary gland adenoid cystic carcinoma and esophageal squamous cell carcinoma." (PMID 29868478, 2018). "In patients with esophageal squamous cell carcinoma (ESCC), a low level of SFN is associated with a poorer prognosis and survival rate." (PMID 36160032, 2022). "In esophageal squamous cell carcinoma (OSCC), downregulation of SFN has been shown to be associated with β-catenin expression, proliferation, invasion depth, lymph node metastasis and has been shown to have potential as a prognostic biomarker for OSCC." (PMID 30404157, 2018).
lymph node metastasis (4 papers, 2014 to 2025). "The aim of this study was to investigate the association between the sFN expression quantity and the frequency of lymph node metastasis in thyroid malignancies, by performing MoAb JT-95 staining in PTC and FTC cases, including follicular type tumors and lymph node metastasis regions." (PMID 24696692, 2014). "We had previously compared the expression profiles of AIS with those of eIA showing lymph node metastasis or a fatal outcome, and found that stratifin (SFN, 14-3-3 sigma) was a differentially expressed gene related to cell proliferation." (PMID 26223682, 2015). "On the other hand, the increasing amount of sFN detected by JT-95 correlated to the lymph node metastasis in thyroid carcinomas." (PMID 24696692, 2014). "Notably, decreased SFN expression was also found to be correlated with lymph node metastasis." (PMID 40004538, 2025).